LRRC10B (leucine rich repeat containing 10B)
Tractability: No criterion of Open Targets' tractability assessment is met for any kind of drug.
Gene: Protein-coding gene on chromosome 11 (61,508,749 to 61,511,018, forward strand). Ensembl gene ENSG00000204950.
Subcellular location (Human Protein Atlas): Nucleoplasm; Nucleoli
Genetic constraint (gnomAD): Loss-of-function variants: 2 observed, 1.81 expected, observed/expected ratio (o/e) 1.1, 90% interval 0.39 to 1.89. That is too few expected variants to judge how well the gene tolerates losing a copy. Missense variants: 389 observed, 340.29 expected, observed/expected ratio (o/e) 1.14, 90% interval 1.05 to 1.24. Synonymous variants: 204 observed, 161.86 expected, observed/expected ratio (o/e) 1.26, 90% interval 1.12 to 1.41.
Homologues: Orthologues: chimpanzee LRRC10B (99% identical), macaque LRRC10B (99% identical), mouse Lrrc10b (95% identical), rat Lrrc10b (95% identical), pig LRRC10B (93% identical), guinea pig LRRC10B (91% identical), tropical clawed frog lrrc10b (48% identical). Paralogues in human: LRRC10 (36% identical), SCRIB (31% identical), LRRC1 (27% identical), ERBIN (27% identical), LRRC7 (26% identical), PHLPP1 (26% identical), MFHAS1 (25% identical), PHLPP2 (25% identical), PIDD1 (25% identical), LRCH4 (25% identical), SHOC2 (24% identical), LRRC8B (23% identical), and 19 more.
Diseases named in the same sentence as LRRC10B in open-access papers:
LRRC10B is named in the same sentence as 4 diseases in open-access papers, as found by Europe PMC text mining. Sharing a sentence is not in itself a finding about the gene and the disease. The quoted sentences say what the papers report.
Hypertension (1 paper, 2021). The presence of chronic increased pressure in the systemic arterial system. "In summary, the present study showed that DNA methylation in the promoters of PRDM6, HDAC9, IGFBP3, LRRC10B, SYT7, PDE3A, TBX2 and C17orf82 genes were significantly associated with BP or hypertension." (PMID 35087571, 2021).
ischemic stroke (1 paper, 2022). A stroke disorder caused by obstruction of blood flow to the brain, due to thrombotic (local blood clot formation) or embolic (due to a blood clot or other material traveling from another site) event. "Each 5% higher methylation level of targets PRDM6_4, LRRC10B_1 and SYT7_1 was associated with a 64% (adjusted OR = 0.36, 95% CI: 0.30–0.43), 51% (adjusted OR = 0.49, 95% CI: 0.41–0.58) and 71% (adjusted OR = 0.29, 95% CI: 0.25–0.34) decreased risk for ischemic stroke, respectively." (PMID 35345488, 2022). "Higher methylation levels of 18 targets in AMH, C17orf82, HDAC9, IGFBP3, LRRC10B, PDE3A, PRDM6, SYT7 and TBX2 genes were associated with a lower risk of ischemic stroke." (PMID 35345488, 2022). "Methylation of AMH, C17orf82, HDAC9, IGFBP3, LRRC10B, PDE3A, PRDM6, SYT7 and TBX2 was significantly associated with ischemic stroke." (PMID 35345488, 2022). "According to the results from stage one and stage two, we confirmed that higher methylation levels of 17 targets in AMH, C17orf82, HDAC9, IGFBP3, LRRC10B, PDE3A, PRDM6, SYT7 and TBX2 genes were associated with a lower risk of ischemic stroke." (PMID 35345488, 2022). "The results showed that the mean methylation levels of AMH, C17orf82, HDAC9, IGFBP3, LRRC10B, PDE3A, PRDM6, SYT7 and TBX2 were significantly (Wilcoxon's two sample test) lower in ischemic stroke cases than in controls." (PMID 35345488, 2022).
LRRC10B also shares sentences with these, for which no sentence is quoted: deafness (1 paper); tumor (1).